CRP (C-reactive protein)
Diseases named in the same sentence as CRP in open-access papers (continued):
Sharing a sentence is not in itself a finding about the gene and the disease.
malnutrition (continued). "Previous studies have demonstrated a strong association between circulating inflammatory markers, such as CRP, IL-6, IL-10, and TNF-α, and malnutrition." (PMID 38474705, 2024). "In the female participants, those with low iron tended toward DM and malnutrition–inflammation, followed by higher MIS, higher UPCR, lower Hb, lower albumin, elevated WBC, elevated CRP, and elevated HbA1c in comparison with those with normal iron." (PMID 36983703, 2023). "Conversely, increased levels of CRP and its end products, tumor necrosis factor-alpha (TNF-α) and interleukin-6 (IL-6), lead to decreased levels of the malnutrition marker albumin." (PMID 37760482, 2023). "The risk factors of sarcopenia in these studies were age, longer disease duration, malnutrition, DAS28, C-reactive protein, and rheumatoid factor seropositivity." (PMID 37239687, 2023). "For the patients with malnutrition as determined by both the GLIM criteria and the SGA, there was a predominance of males, Charlson comorbidity index scores were higher, and CRP levels were higher." (PMID 37764796, 2023). "In our study, the tercile 3 group had the most prolonged QTc interval and higher proportions of type 2 DM, CAD, HFrEF, dialysis, advanced limb ischemia, malnutrition, elevated NLR, and CRP." (PMID 37252112, 2023). "Nevertheless, our study results indicated that although CRP had the highest AUC for the malnutrition, the SARC-F score can correlate with the CONUT score in patients with GDs as well as CRP." (PMID 35160034, 2022). "There was a positive correlation between malnutrition based on GLIM criteria, serum albumin, and CRP." (PMID 35276861, 2022). "The GLIM-diagnosed malnutrition was positively related to age, NRS 2002 and PG-SGA scores, direct bilirubin and C-reactive protein levels, and counts of white blood cells and neutrophils (all p < 0.05)." (PMID 36501196, 2022). "Malnutrition preceded CUA onset, with a median albumin decrease of 2.7 g/L within the 6 months before onset and C-reactive protein (CRP) was high at both times." (PMID 32101140, 2020). "We also investigated the association between serum inflammatory markers (IL-6, IL-8, TNF-α, and CRP) and overall functional decline (ADL and TUG) and malnutrition." (PMID 33166358, 2020). "mGPS is calculated from C-reactive protein (CRP) and serum albumin, a common marker of malnutrition and inflammation, and PNI is calculated from serum albumin and total peripheral lymphocyte count." (PMID 33176752, 2020). "Individuals with RLD had higher prevalence of DM (46%), CVD (48%), and malnutrition (SGA>1; 31%), lower %HGS, higher concentrations of CRP and IL-6, and lower GFR." (PMID 29702682, 2018). "The data showed that BMI, FM, and serum albumin decreased significantly in malnutrition group (BMI, P = 0.013; FM, P = 0.039; albumin, P = 0.037), while CRP and MIS significantly increased (CRP, P = 0.008; MIS, P = 0.000)." (PMID 24349471, 2013). "However, serum albumin concentrations may be influenced by malnutrition, hydration status and trans-capillary escape, as well as the presence of an inflammatory response, and therefore serum CRP concentrations were chosen for entry into the multivariate analysis." (PMID 19127266, 2009). "Additionally, other biomarkers like prealbumin, C-reactive protein, and CRP/prealbumin ratio have been proposed as potential tools to differentiate between inflammation and malnutrition." (PMID 40572732, 2025). "The CRP/ALB ratio may, therefore, be a useful marker for assessment of critically ill patients, as it effectively reflects both inflammation and malnutrition." (PMID 40573094, 2025). "Moreover, increased CRP levels, which is a marker of systemic inflammation, plays a dual role as it may not only reflect disease activity but also contribute directly to the pathogenesis of disease-related malnutrition through catabolic and anorexigenic pathways." (PMID 40871731, 2025).
malnutrition (continued). "In our study, we did not specifically examine the impact of elevated CRP on malnutrition, so we cannot draw direct conclusions in this regard." (PMID 40566551, 2025). "The presence of malnutrition status and sarcopenia is also supported by lower values of proteins as well as of serum albumin and CPK and by a chronic status of inflammation, expressed by a significant increment in CRP and neutrophil values." (PMID 38786972, 2024). "Our discoveries showed that esophageal cancer patients without malnutrition had lower levels of the inflammatory marker CRP and higher levels of ALB than those with malnutrition." (PMID 39070256, 2024). "Reduced albumin and pre-albumin levels should not be considered a sign of malnutrition in the presence of an acute response (e.g., elevated CRP) when they serve as negative markers of acute response." (PMID 39308920, 2024). "In support of this hypothesis, it should be remembered that MIS is actually an integrated score of malnutrition and inflammation and proof of this is the fact that in our population, MIS is directly correlated with CRP values." (PMID 39203763, 2024). "MIS, malnutrition inflammation; ESAS, Edmonton Symptom Assessment System; BMI, body mass index; CRP, C-reactive protein; a balance SPPB domain; b gait velocity SPPB domain; c chair stand capacity SPPB domain; d total SPPB score; P sarcopenic versus non-sarcopenic difference; *P < 0.05, **P < 0.01." (PMID 39723266, 2024). "Inflammation was assessed using the CRP value for all but four patients, for whom inflammation was determined using clinical criteria (one met the criteria for malnutrition according to the GLIM criteria, but the rest did not)." (PMID 37764796, 2023). "The average CRP level among residents with malnutrition was 1.95 mg/dL, compared to 2.07 mg/dL among non-malnourished residents." (PMID 37892441, 2023). "Moreover, PNI was inversely correlated with platelet count, CRP, NLR, C/NLR and PLR, whereas it was positively correlated with LMR, suggesting that tumor-induced chronic inflammation and malnutrition coexist in patients with MPM." (PMID 37002247, 2023). "Other biochemical parameters, e.g., serum lipids, total iron binding capacity (TIBC), and C-reactive protein (CRP), are readily used as malnutrition-inflammation markers, while serum potassium and phosphorus levels are monitored safety parameters in HD patients." (PMID 37927500, 2023). "However, almost all included studies were conducted in high-income countries, and PCT and CRP have been suggested to be influenced by HIV, malaria, and malnutrition." (PMID 36963048, 2023). "Unlike CRP, Alb is the most abundant protein in blood serum, produced by the liver, and its concentration decreases in malnutrition and inflammation." (PMID 37433824, 2023). "We propose the use of the American society of anesthesiologists classification of physical status (ASAPS), C-reactive protein (CRP), and neutrophil-lymphocyte ratio (NLR) to discriminate clean malnutrition, disease-related malnutrition (DRM) with inflammation, and DRM without inflammation." (PMID 38024369, 2023). "We used mGPS, a two-dimensional measure of malnutrition and systemic inflammation, including positive and negative acute phase reactants (CRP and albumin), as a prognostic indicator." (PMID 37836440, 2023). "In the model assessing the odds of severe malnutrition according to the criteria of GLIM, TLC and CRP had a statistically significant effect on the chance in the probability of qualifying a patient to the severe malnutrition group, but the strength of the results was weak." (PMID 35276861, 2022). "In the univariate analysis of variables for the CONUT score ≥ 2 (mild or more advanced malnutrition), age (p = 0.0485), BMI (p = 0.020), SARC-F score (p < 0.0001), estimated glomerular filtration rate (eGFR, p = 0.0020), and C reactive protein (CRP, p < 0.0001) were significant factors." (PMID 35160034, 2022).
malnutrition (continued). "Patients with malnutrition had lower BMI, red blood cells, hemoglobin, lymphocytes, and higher C-reactive protein and platelet-to-lymphocyte ratio than patients without malnutrition in both cohorts." (PMID 35745139, 2022). "Low serum prealbumin levels indicate the presence of acute inflammation and/or malnutrition, unlike other biomarkers such as CRP and PCT that predominantly reflect the inflammatory burden." (PMID 36558522, 2022). "According to PNI, malnutrition was more prevalent in the high-flow therapy group (94.9%; P < 0.001) with significantly lower PNI compared to both groups even after adjusting for the center and C-reactive protein." (PMID 35479742, 2022). "Clinical and nutritional monitoring was performed by malnutrition-inflammation score (MIS), biochemical parameters (s-albumin, s-prealbumin, and serum C-reactive protein (s-CRP), body composition measured by bioelectrical impedance analysis (BIA), anthropometry, and handgrip strength measurements." (PMID 36145223, 2022). "It is screened considering various factors such as weight loss in the last six months, upper arm circumference, triceps skinfold thickness, strength in the handgrip, C-reactive protein (CRP) levels, and screening tools such as malnutrition universal screening tool (MUST)." (PMID 35971351, 2022). "Likewise, in the univariate analysis of variables for the CONUT score ≥ 5 (moderate or more advanced malnutrition), the SARC-F score (p < 0.0001), eGFR (p = 0.0010) and CRP (p < 0.0001) were significant factors." (PMID 35160034, 2022). "C-reactive protein (CRP) is indicated as an indicator of high inflammation, and low albumin is a negative phase reactant indicating malnutrition." (PMID 35070560, 2021). "The MIRT, which includes BMI, weight loss and CRP, has been validated against the subjective global assessment (SGA), which is used to assess current malnutrition and not to predict future risk of malnutrition." (PMID 34836353, 2021). "Interestingly, despite differences in age, BMI and CRP levels between patients with and without poor prognosis based on a physical surrogate, the present study shows that especially relative measures of exercise capacity are associated with malnutrition and inflammation." (PMID 32730305, 2020). "Objective measures were used (including fat free mass index and C-reactive protein) to determine a diagnosis of malnutrition using the GLIM criteria, with results demonstrating a malnutrition prevalence of between 0.5 and 32.4% depending on the time point and criterion combination used." (PMID 33203000, 2020). "Increased CRP, NT-proBNP, and OH/ECW in malnutrition group means that nutrition, hydration, and inflammation were correlated but we could not determine the causal relationship." (PMID 30089153, 2018). "When we stratified these patients according to nutritional status evaluated by SGA, the ‘mild to severe malnutrition’ group was significantly older and had more females, lower hemoglobin, serum albumin and creatinine levels, but higher BUN and hs-CRP levels than the ‘good nutrition’ group." (PMID 30552374, 2018). "Laboratory examination revealed that non-surviving patients had malnutrition status, reduced total protein (TP) and albumin (Alb) levels, and elevated inflammatory markers, such as C-reactive protein (CRP) and serum amyloid A (SAA), in the peripheral blood." (PMID 30177769, 2018). "GPS, a combination of CRP and ALB, is an excellent index of system inflammation and malnutrition." (PMID 29100345, 2017). "CRP and TLC failed to distinguish patients at risk of malnutrition defined by any of the tools, although their concentration reflected the presence of inflammatory response, even when acute patients are removed." (PMID 28771192, 2017). "This child, who had a CRP level of 81.3 mg/L, was 5 months of age from the Mali site with no signs of illness or malnutrition and no apparent factors for elevated CRP." (PMID 28575375, 2017).
malnutrition (continued). "Last, but not least important, no blood chemistry data were available to calculate Kt/V or urea reduction rate and no CRP (C-reactive protein) or albumin level data were available to determine the status of inflammation or malnutrition, respectively." (PMID 27240348, 2016). "The effect of malnutrition on low plasma selenium also decreased according to the CRP concentration increase and was no longer significant from values >40 mg/L." (PMID 24886623, 2014). "It is also likely that this malnourished study population has elevated CRP and MDA due to nutritional deficiency or unrecognized lung infection and not because of exposure to biomass smoke." (PMID 23777718, 2013). "While CRP was associated with various nutritional parameters such as reduced dietary intake and weight loss, neither IL- 6 nor TNF-α showed a significant association with malnutrition risk parameters according to the NRS total score or its components." (PMID 40275239, 2025). "Both CRP and albumin contribute to the CAR increase in this study, this being representative of progressive right-heart failure with systemic congestion, intestinal impairment with malnutrition, and low-grade systemic inflammation described by the other studies." (PMID 40208300, 2025). "If CRP is only used for screening and not for the severity grading of malnutrition, it may be reasonable for clinical practice to use a rough and low cut-off value, such as a CRP value of 3–4 mg/dL, in critically ill patients." (PMID 40005032, 2025). "Additionally, this study will compare the correlations between GHRL, MSTN, C-reactive protein (CRP), and high-sensitivity C-reactive protein (Hs-CRP), to further elucidate the potential relationship between malnutrition/muscle wasting disease and inflammatory pathophysiological mechanisms." (PMID 40813643, 2025). "Furthermore, the mean age, number of hospitalization days, and CRP values of the group with NRS-2002 scores of 3 and above were found to be statistically significantly higher than in the group without malnutrition risk." (PMID 40507738, 2025). "According to the GPS value, which reflects both the inflammatory and nutritional status, calculated using ALB and CRP levels, we observed the same particularity in both groups that most patients (16/25 CR-NET patients and 39/60 CRC patients, respectively) had mild to moderate malnutrition." (PMID 39000088, 2024). "We found a significant increase in serum GDF15 levels in AECOPD patients with malnutrition, which was negatively correlated with nutritional indicators such as BMI, MAC, CC, TP, ALB, and PNI, while demonstrating a positive correlation with the inflammatory marker CRP." (PMID 39050134, 2024). "But its definition was based on body weight loss, lower BMI, low calorie intake, with a low albumin and high CRP levels, and such definition may not clarify the severity of malnutrition." (PMID 39702125, 2024). "Prevalence values of malnutrition identified with GLIM criteria documented in Caucasian geriatric populations range from 46.6% in a group of 60 Swiss geriatric rehabilitation patients with GLIM1 and CRP > 10 mg/L to 64% in Swedish geriatric patients with GLIM1 criteria." (PMID 38674807, 2024). "Furthermore, in this case, the simple PEW score, CRP, and CTR can reflect malnutrition, inflammation, and fluid volume, respectively, and these factors may interact with each other." (PMID 37652929, 2023). "Therefore, AMI combined with malnutrition can further aggravate myocardial injury and inflammatory reactions, which is consistent with the findings that troponin, BNP, and CRP significantly increased and LVEF significantly decreased in the PNI-L subgroup at the baseline during our study." (PMID 37875955, 2023).
malnutrition (continued). "The presence of more elevated levels of inflammatory markers, including serum ferritin and C-reactive protein was observed in patients with malnutrition in comparison to those without malnutrition (301.2 ± 127.1 mg/dL vs. 212.7 ± 124.9 mg/dL, p < 0.05; 63% vs. 33%, p < 0.05)." (PMID 31979104, 2020). "In addition, frail older patients who were hospitalized had lower levels of albumin, which is a marker of malnutrition, and higher levels of CRP and IL-6 than non-frail individuals." (PMID 30249038, 2018). "The cross-sectional nature of the study was limited in that it provided a “snapshot” and could not determine if malnutrition and inflammation preceded disease and changes in BMI and CRP levels." (PMID 30065944, 2018). "However, it is important to emphasize that our study, similarly to all other large cohort studies, does not have data related to malnutrition and inflammation, such albumin, CRP, IL-6 or any other marker." (PMID 26091005, 2015). "However, the findings with CRP indicate that HGS measurements might not be a reliable indicator of FFM or malnutrition in patients with severe or active disease." (PMID 34464858, 2021). "This prompt questions regarding some of the individual results, as certain malnutrition criteria, such as standard FFMI cutoffs and CRP, are not well-suited for individuals with SCI in the chronic phase." (PMID 38571922, 2024). "CRP and albumin are not just the components of the immune-inflammation index CAR, but they are also strong predictors of liver function, malnutrition, and eventual WL in cancer patients, which can lead to deadly cachexia." (PMID 38975012, 2024). "It has been proposed that prealbumin is not interpretable as a nutritional marker when the CRP level is higher than 15 mg/dL, while if the CPR level is lower, prealbumin allows for the detection of malnutrition and the degree of malnutrition." (PMID 39203747, 2024). "In two studies of Crohn’s disease, CRP levels were significant between the two groups of patients, as defined by the GLIM criteria, but neither was an independent factor for malnutrition." (PMID 37736137, 2023). "Similarly, regression analysis results suggested that both CRP and ESR are lacking specificity in the diagnosis of malnutrition." (PMID 36742004, 2022). "Continuously high-levels of CRP may stimulate SIRS and high metabolic reactions, resulting in malnutrition and a lack of structural proteins, exacerbating the disease process." (PMID 25780458, 2015). "However, Hickson claims that CRP, TLC, and WBC levels may only serve as indicators of inflammation and are not good indicators of malnutrition." (PMID 37111024, 2023).